CTLA4 (cytotoxic T-lymphocyte associated protein 4)
Diseases named in the same sentence as CTLA4 in open-access papers (continued):
Sharing a sentence is not in itself a finding about the gene and the disease.
breast tumor (continued). "In conclusion, our study shows that multiple immune checkpoints including PD-1, CTLA-4, TIM-3, and LAG-3 are upregulated in breast tumor tissues." (PMID 29983831, 2018). "This study critically advances our knowledge of the epigenetic modifications behind the transcriptional upregulation of PD-1, CTLA-4, TIM-3, LAG-3, TIGIT, and PD-L1 in breast tumor tissues." (PMID 29983831, 2018). "To quantify the binding intensity of H3K9me3 and H3K27me3 on the promoters of PD-1, CTLA-4, TIM-3, and LAG-3 in normal and breast tumor tissues, we performed a ChIP-qPCR analysis using H3K9me3 and H3K27me3 antibodies." (PMID 29983831, 2018). "In our study, we checked the expression of immune checkpoints/ligand including PD-1, CTLA-4, TIGIT, TIM-3, LAG-3, and PD-L1 and found that PD-1, CTLA-4, TIM-3, and LAG-3 were upregulated in breast tumor tissues, compared with normal tissues." (PMID 29983831, 2018). "We first assessed the expression level of six immune checkpoints/ligands and found that PD-1, CTLA-4, TIM-3, and LAG-3 were significantly upregulated in breast tumor tissues (TT), compared with breast normal tissues (NT)." (PMID 29983831, 2018). "CTLA-4 was overexpressed in breast tumors and invasive ductal carcinomas, with no such overexpression observed in benign breast tissues." (PMID 41141615, 2025). "A recent preclinical study demonstrated that combining cytotoxic agents with CTLA4 inhibition and CD40 agonists may be more effective than targeting multiple checkpoints on T cells, especially in cold lesions as most TN breast tumors." (PMID 39103878, 2024). "To evaluate the generalizability of our observations, we tested the therapeutic efficacy of the triple combination of PIC + RT + anti-CTLA-4 in the MyC-CaP prostate tumor model in syngeneic male FVB/NTac mice and the orthotopic TC11 breast tumor model in syngeneic female FVB/NTac mice." (PMID 35999216, 2022). "However, an LS diet did not induce any significant irAE response in breast-tumor-bearing mice upon treatment with anti-CTLA4 mAb, thus suggesting the role of high-salt diet in irAE response." (PMID 35741331, 2022). "This may be due to the fact that CTLA-4 and PD-1 are considered to be both activation and exhaustion markers and are upregulated when T cells are chronically exposed to non-self-tumor antigens (as is the case in our model of 4T1 breast tumor growth)." (PMID 33584650, 2020).
thyroiditis (51 papers, 2009 to 2025). Inflammation of the thyroid gland. "They observed that PD-1 inhibition triggered more severe thyroiditis with significantly elevated IL-6, whereas CTLA-4 blockade was associated with increased GM-CSF/MIP-1β and diffuse thyroid enlargement." (PMID 40909293, 2025). "The blockade of both CTLA-4 and PD-1 was associated with a high risk of irAEs including hypopituitarism and thyroiditis." (PMID 35468815, 2022). "Numerous investigations provided data that CTLA-4 is linked to autoimmune diseases such as Graves’ disease, type 1 diabetes, thyroiditis, and lupus erythematosus." (PMID 32580338, 2020). "Thyroid disorders are one of the most common adverse events caused by anti-PD-1 monotherapy or combinatorial therapy of anti-CTLA-4 plus anti-PD-1." (PMID 32528284, 2020). "Disease susceptibility, for example in thyroiditis, is attributed to a non-coding region of the CTLA4 gene and a variation in gene splicing." (PMID 31653079, 2019). "Notably, compared to CTLA-4 and PD-L1 inhibitors, PD-1 inhibitors are associated with a higher incidence of thyroid disorders." (PMID 40951340, 2025). "Subsequent investigation revealed increased IL17A+ T cells in secondary lymphoid tissues of combined anti-PD-1 and anti-CTLA-4 treated mice compared with isotype control, suggesting that cytokine production from RORγ+ Th17 and Tc17 was associated with thyroiditis." (PMID 39247203, 2024). "We encountered a rare case of thyrotoxicosis caused by painless thyroiditis and secondary adrenal insufficiency (AI) occurring simultaneously after the combined use of two ICIs; nivolumab, an anti-PD-1 antibody, and ipilimumab, an anti-CTLA-4 antibody." (PMID 38910605, 2024). "The application of immune checkpoint inhibitors such as programmed death 1 (PD-1), programmed death ligand 1 (PDL-1), and cytotoxic T-lymphocyte antigen 4 (CTLA-4) antibodies has previously been reported to be associated with immune-related adverse events such as thyroid dysfunction and thyroiditis." (PMID 36389794, 2022). "Thyroid irAEs are more common with programmed cell death protein-1 (PD-1) inhibitor or programmed cell death-ligand 1 (PD-L1) inhibitors than cytotoxic T-lymphocyte-associated protein 4 (CTLA-4) inhibitors." (PMID 37908246, 2022). "In addition, it is known that polymorphisms of PD-1 and CTLA-4 are associated with various autoimmune diseases such as thyroiditis, diabetes mellitus, rheumatoid arthritis, and even myasthenia gravis." (PMID 31653079, 2019). "The incidence rate is highest with combination therapy and lowest with CTLA-4 inhibitors, This suggests that differences in the mechanism of action of ICIs are associated with the varied incidence of ICI-induced thyroiditis." (PMID 40535343, 2025). "In another recent study using NOD-H2h4 mice, thyroiditis was more prevalent with anti-CTLA-4 treatment, but more severe symptoms were seen following anti-PD-1 administration and was correlated with immune cell infiltration in thyroidal tissues." (PMID 39247203, 2024). "Our findings suggest that there is a genetic relationship between the CTLA-4 (+55A/C) genotype and the seropositivity against thyroid autoantigens, such as anti-thyroid peroxidase (ATPO) and anti-thyroglobulin antibodies (ATG)." (PMID 37568880, 2023). "In monotherapy clinical trials, thyroiditis was more common after blockade of the PD-1/PD-L1 pathway with an incidence of 8–38% compared to CTLA-4 inhibition with an incidence of 6–25%." (PMID 38136348, 2023). "ICI-induced thyroiditis is more frequent after PD-1 compared with CTLA-4 blockade (10-20.4% versus 1.5-9%)." (PMID 35912205, 2022). "GWAS have demonstrated key susceptibility genes implicated in both immune regulation and increased risk of ICI-induced thyroiditis, including CD69, CTLA4, PTPN22 and LPP." (PMID 35912205, 2022). "The dynamic evolution of thyroid disorders has also been assessed in 45 patients who received anti-PD-1 monotherapy or anti-CTLA-4/anti-PD-1 combinatorial therapy." (PMID 32528284, 2020).
thyroiditis (continued). "Nevertheless, other studies demonstrated a major prevalence of thyroid disorders in patient treated with anti-PD-1 and a higher rate of pituitary disorders in those treated with anti CTLA-4." (PMID 32294888, 2020). "In murine EAT, tolerance induction with the known autoantigen, mouse Tg, and its blockade of nTreg activation by anti-CTLA-4 to allow thyroiditis development can be followed with timed co-administration." (PMID 24904570, 2014). "Despite extensive investigations of CTLA-4 SNPs, the association between +22A/G rs231775 SNP and thyroid auto-antibody production in Asian patients has not been demonstrated." (PMID 37568880, 2023). "Thyroid irAEs from ICIs are more common with PD-1/PD-L1 inhibitors than with CTLA-4 inhibitors." (PMID 35744922, 2022). "The immune checkpoint PD-1/PD-L1 axis (CTLA-4, TIGIT, TIM3) activation played an important part in thyroid carcinogenesis." (PMID 37798795, 2023). "In hepatocellular carcinoma, follicular lymphoma, thyroid and high-grade serous ovarian cancer, PD-1 is upregulated on CXCR5+CD8 T cells while TIM3 and CTLA4 are downregulated compared to CXCR5−CD8 T cells possibly indicating a Tpex versus Tex phenotype." (PMID 36314014, 2022). "Of note, prior treatment with CTLA-4 inhibitors or PD-1 inhibitors did not appear to prime the thyroid for thyroiditis events after cICI." (PMID 38136348, 2023). "Linkage of the CTLA-4 region with thyroid autoantibody production in patients with and without clinical thyroid disease has been demonstrated." (PMID 23154164, 2013). "However, a study carried out in 2022 shows that CTLA4 is not involved in the pathogenesis of HTLV-1-related thyroiditis." (PMID 37293205, 2023). "For example, combination strategies that target multiple aspects of the immune response (e.g., PD-1/PD-L1 and CTLA-4 pathways) or tumor cells themselves (e.g., tyrosine kinase inhibitors, BRAF inhibitors, radiotherapy) could provide benefits for patients with advanced thyroid disease." (PMID 31412566, 2019).
leukemia (47 papers, 2006 to 2026). A malignant (clonal) hematologic disorder, involving hematopoietic stem cells and characterized by the presence of primitive or atypical myeloid or lymphoid cells in the bone marrow and the blood. "Regarding CTLA4, its deficiency improved proliferation and anti-tumor efficacy in preclinical models of leukemia and myeloma, rescuing the function of T cells from patients with leukemia who previously failed CAR-T cell treatment." (PMID 40861448, 2025). "Previous studies have demonstrated that whole leukemia cell vaccines are suppressed by various immunosuppressive mechanisms of leukemia, including B7/cytotoxic T lymphocyte-associated protein 4 (CTLA4) and PD-1/PD-L1, Tregs, and myeloid-derived suppressor cells (MDSCs)." (PMID 35074008, 2022). "Our meta-analysis suggested that the CTLA-4 49A/G polymorphism is associated with a decreased NHL, multiple myeloma, and leukemia risk, while the CTLA-4 319C/T polymorphism is significantly associated with a decreased CLL risk." (PMID 39464701, 2024). "An older study of this syndrome showed that in people with the CD38+ phenotype who had lower CTLA-4 expression, leukemia had a mild course." (PMID 35158937, 2022). "CD19 CAR-T cells used for treatment of B cell lymphomas and leukemias upregulate suppressive receptors such as CTLA-4 and PD-1 which limit their activation and cytotoxicity." (PMID 34722633, 2021). "The association between CTLA-4, ICOS, and CD28 polymorphisms and leukemia risk were assessed among Iranian patients." (PMID 32375828, 2020). "CTLA-4/CD80/CD86—hampering T cell immunity against hematological malignancies and modulating immune responses in AML.Blocking of CTLA-4 pathway—increase of anti-leukemia T-cell immune response translated in prolonged tumor regression." (PMID 31649875, 2019). "Blocking CTLA-4 and blocking PD-1/PD-L1 pathway with anti PD-L1 antibody enhanced the anti-leukemia immune response in mice." (PMID 31616632, 2019). "Decitabine, a hypomethylating agent, upregulated PD-1, PD-L1, PD-L2 and CTLA-4 protein and RNA transcription in leukemia patients and dose-dependently increased these same ligands in leukemia cell lines." (PMID 27854240, 2016). "For example, combining JAK2 inhibitors with immune checkpoint inhibitors such as anti-PD-1 or anti-CTLA-4 antibodies could enhance the immune response against leukemia cells." (PMID 40486651, 2025). "The pooled results suggested the CTLA-4 49A/G polymorphism was significantly associated with an increased hematologic malignancy risk (AA vs. GA+GG: OR = 1.77, 95% CI = 1.56-2.02), especially in NHL, multiple myeloma, and leukemia." (PMID 39464701, 2024). "CTLA4 deficiency in CAR-T cells improved proliferation and anti-tumor efficacy in preclinical models of leukemia and myeloma, which rescued the function of T cells from patients with leukemia that previously failed CAR-T cell treatment." (PMID 39134804, 2024). "In addition, increased CD4+CD25+FOXP3+CTLA-4+ Tregs occurring alongside leukemia development were described in the Eμ-TCL1 transgenic mouse model of CLL." (PMID 39335199, 2024). "Therefore, we proved that stimulatory and inhibitory interactions between effector cells and lymphoblastic target cells guide T-cell function against leukemia through CD80/86–CD28/CTLA-4 as well as PD-1–PD-L interactions." (PMID 27708227, 2016). "CTLA-4 expressed on donors’ T cells plays the crucial role in the regulation of the immune response, in particular, in the graft versus leukemia effect and in controlling infections; therefore, the majority of studies have focused on the donor CTLA-4 gene polymorphism." (PMID 25940108, 2015). "Especially, combining DC-based immunotherapy with the blockade of immune checkpoint regulators such as PD-1 and/or CTLA-4 may represent a powerful tool for the treatment of leukemia." (PMID 24427158, 2013).
leukemia (continued). "Currently, there are several studies of CTLA-4 blockade in patients who have either relapsed or who have persistent leukemia following allogeneic stem cell transplant (NCT00060372, NCT01822509), though to our knowledge, PD-1 blockade in the post-transplant setting has not yet been tested in humans." (PMID 24353898, 2013). "Also, the cytotoxic T lymphocyte-associated antigen-4 (CTLA-4), a regulator of the effector function of T cells, is expressed in various leukemias and solid tumors." (PMID 16478542, 2006). "Therefore, blockade of the CTLA4 and PD-1 pathways could be used in combination with whole leukemia cell vaccines." (PMID 35074008, 2022). "Restored expression of Tbet and a Tbet dependent increase in IFN-γ and CXCR3 expression was also found after combined check-point blockade (PD-1, CTLA-4, and LAG-3) in a murine leukemia model." (PMID 33193386, 2020). "Therefore, monoclonal antibodies blocking CTLA-4 on the surface of T cells including Tregs from CLL patients can augment anti-tumour immunity, and CTLA-4 blockade may represent a therapeutic opportunity to enhance the immune responses against autologous leukaemia cells." (PMID 26490985, 2016). "We saw a moderate but solid reduction in stem cell-like cells with the checkpoint inhibitors CTLA4 or PD-1 alone, and again we saw that the combination of these immunotherapeutics did not enhance these anti-leukemia effects." (PMID 41145674, 2026). "Immune monitoring showed generation of mature DCleu, activation of leukaemia-directed effector and memory cells (including IFN-γ-producing and degranulating T and NK cells), downregulation of immune checkpoint (PD-1/CTLA-4) expressing T cells and blasts, and a reduction in regulatory B- and T cells." (PMID 40817367, 2025). "Strategies that block immune checkpoint molecules such as PD-1 or CTLA-4 may also synergize with JAK2 inhibitors, enhancing immune-mediated leukemia elimination." (PMID 40486651, 2025). "Moreover, we suggest also that not only the cells that overexpress CTLA-4 and TIM-3, but even those that overexpress CD39, TIGIT, and TNFR2, favor B-ALL leukemia growth." (PMID 36901957, 2023). "Therefore, the correlation of CD39, CTLA-4, TIGIT, TIM-3, and TNFR2 with Ki-67 suggested that their overexpression in Treg and/or exhausted CD8+ T cells of patients with ALL favors leukemia development and treatment resistance." (PMID 36901957, 2023). "Only higher expression of CTLA-4 on CD8+ T cells was observed in patients with relapse (n=7) during the first year after allo-SCT (p=0.021) as compared to patients without leukemia relapse (n=17)." (PMID 36824620, 2022). "Since CTLA-4 is involved in regulation of proliferation and cell survival, an intriguing question is whether the peripheral blood leukaemia cells from CLL patients differ in terms of the proliferation activity and apoptosis before as well as after ex vivo stimulation regarding CTLA-4 expression." (PMID 26490985, 2016). "For example, PD-1 and CTLA-4 blockade was recently shown to prevent the deletion of tumor-reactive T cells, whereas additional blockade of LAG-3 was vital to promote greater effector function among these persisting TIL – providing a clear survival benefit for leukemia-bearing hosts." (PMID 24353898, 2013).
Hodgkins lymphoma (45 papers, 2004 to 2025). A heterogeneous group of malignant lymphoid neoplasms of B-cell origin characterized histologically by the presence of Hodgkin and Reed-Sternberg (HRS) cells in the vast majority of cases. "This association demonstrates that CTLA-4-mediated suppression of antitumor T cell activation leads to a survival advantage and proliferation of immune cells in the tumor microenvironment of Hodgkin lymphoma." (PMID 37305822, 2023). "ICIs, notably PD-1 inhibitors (e.g. nivolumab, pembrolizumab) and CTLA-4 inhibitor ipilimumab, are now standard in some hematologic contexts (for example, PD-1 blockers in relapsed/refractory Hodgkin lymphoma) and are being investigated in others." (PMID 41568391, 2025). "mAbs targeting CTLA-4 or PD-1 have demonstrated notable clinical efficacy in patients with HMs, particularly in those with Hodgkin’s lymphoma and primary mediastinal B-cell lymphoma." (PMID 39766080, 2024). "Mean CTLA-4 expression was 239.84 ± 76.36 for nodular sclerosis, 293.95 ± 147.94 for mixed cellularity, 271.4 ± 23.56 for lymphocyte depleted, and 225.2 for lymphocyte-rich subtypes." (PMID 38978137, 2024). "This increased expression of CTLA-4 in immune cells was mainly due to the higher percentage of CTLA-4 T cells in the tumor microenvironment of Hodgkin lymphoma." (PMID 37305822, 2023). "The mean density of CTLA-4+ cells was 674 ± 1482 cells/mm2 and ranged from 71 ± 175 cells/mm2 in leiomyoma to 5916 ± 3826 cells/mm2 in Hodgkin’s lymphoma." (PMID 35091676, 2022). "The interference of vaccinia virus-infected cell culture supernatant was confirmed by flow cytometry using the CD80- and CD86-positive human cell line KM-H2 (Hodgkin lymphoma) and soluble recombinant CTLA4-Fc." (PMID 30918073, 2019). "In a phase I clinical trial of ipilimumab after allo-HSCT, complete remission was achieved in two patients with Hodgkin’s lymphoma and partial remission in one patient with refractory mantle cell lymphoma, suggesting that targeting CTLA-4 is feasible." (PMID 27118383, 2016). "Therefore, this study aimed to analyze immune inhibitory molecule CTLA-4 and B7-1 expression in the tumor cells and the microenvironment of Hodgkin lymphoma." (PMID 37305822, 2023). "Similarly, the expression and intensity of CTLA-4 in the immune cells of the nodular sclerosis subtype and lymphocytes-rich subtype showed 1-10% expression and 1+ intensity and 10-50% expression and 2+ intensity, respectively, in most cases." (PMID 37305822, 2023). "In this study, we analyzed the expression and potential role of CTLA-4 and CD80 signaling pathways related to immune suppression and disease progression in the tumor microenvironment of various subtypes of Hodgkin Lymphoma." (PMID 37305822, 2023). "We compared the expression of CTLA-4 and CD80 in the immune cells of the Hodgkin lymphoma microenvironment." (PMID 37305822, 2023). "We found that CTLA-4 expression was higher in T cells than in antigen-presenting cells (APC), and CD80 expression was higher in APC than T cells in the immune cells of the Hodgkin lymphoma microenvironment." (PMID 37305822, 2023). "This study provides pioneering insights into the expression of immune inhibitory molecules CTLA-4 and B7-1 in Hodgkin lymphoma, with no published data from India to compare these findings in our population." (PMID 37305822, 2023).